FGF10 (fibroblast growth factor 10)
Diseases named in the same sentence as FGF10 in open-access papers (continued):
Sharing a sentence is not in itself a finding about the gene and the disease.
esophageal adenocarcinoma (1 paper, 2019). A malignant tumor with glandular differentiation arising predominantly from Barrett mucosa in the lower third of the esophagus. "Use case – Esophageal adenocarcinoma with reported amplification ofCCND1,MAP2K1,RICTOR,FGF10,FGF19,FGF3,FGF4 andMCL1." (PMID 31608148, 2019).
Follicular Cyst (1 paper, 2023). Cyst due to the occlusion of the duct of a follicle or small gland. "The transcriptomic analysis and prediction of upstream regulators in this study showed that FGF7 and FGF10 mRNA was significantly up-regulated in TIMG cells from follicular cysts compared with normal mature follicles." (PMID 38274662, 2023). "Although there are obvious differences between follicular cysts and tumors, we speculate that high levels of FGF7 and FGF10 expression may participate in the formation of follicular cysts in sows through activation of the MAPK signaling pathway." (PMID 38274662, 2023).
gallbladder carcinoma (1 paper, 2017). "AKT2, FGFR3, and FGF10 amplification had been reported in Chinese gallbladder carcinoma." (PMID 28029662, 2017).
Gastric Metaplasia (1 paper, 2012). Intestinal metaplasia of the gastric mucosa is an intermediate precancerous gastric lesion in the gastric cancer cascade from chronic gastritis and atrophy to dysplasia and adenocarcinoma. "Hence, we cannot exclude the possibility that FGF10-FGFR2b signaling may play a role in gastric metaplasia." (PMID 23133671, 2012).
glioma (1 paper, 2018). A benign or malignant brain and spinal cord tumor that arises from glial cells (astrocytes, oligodendrocytes, ependymal cells). "Glioma-associated DEGs DOCK6, ILK, MGMT, NOTCH4 were up-regulated and FGF10, JAK1, JUNB, RHOB were down-regulated uniquely in the mouse." (PMID 29352201, 2018). "Other genes uniquely altered in mouse gliomas (e.g. NOTCH4, FGF10, JUNB, RHOB) may contribute further to murine-specific differences in glioma biology." (PMID 29352201, 2018).
Graves’ orbitopathy (1 paper, 2021). "In this study, we investigated the effect of FGF10 on fibrosis and the inflammation mechanism of Graves′ orbitopathy (GO)." (PMID 34383782, 2021).
hepatoblastoma (1 paper, 2024). Hepatoblastoma (HB) is a malignant hepatic tumor and is the most common pediatric liver cancer. "For the majority of the hepatoblastoma tumoroids (6 of 9 tested), colony formation was abolished in the absence of the standard growth factors usually included in the media (EGF, FGF10, and HGF) or in the presence of a MEK inhibitor, U0126." (PMID 39567523, 2024).
herpes simplex infections (1 paper, 2024). "The top twenty pathways regulated with enrichment of FGF10 gene in bovine adipocytes includes PPAR signaling pathway, bases excision repairs, cells cycle, DNA replications, herpes simplex infections, homologous recombination, apoptosis, and regulation of lipolysis in adipocytes." (PMID 37946430, 2024).
hypothyroidism (1 paper, 2020). Abnormally low levels of thyroid hormone. "Although the generated thyroid tissues in Fgf10 Ex1mut/Ex3mut chimeras were mixtures of donor and host cells, this is not an argument against thyroid regeneration, because transplantation of mature thyroid follicular cells (not the organ) would suffice as therapy for patients with hypothyroidism." (PMID 33381086, 2020).
intestinal atresia (1 paper, 2020). A congenital malformation characterized by the absence of a normal opening in a part of the intestine. "We focus on research regarding FGF10/FGFR2b signaling and its role in duodenal and other intestinal atresia." (PMID 32210824, 2020).
ischemic stroke (1 paper, 2016). A stroke disorder caused by obstruction of blood flow to the brain, due to thrombotic (local blood clot formation) or embolic (due to a blood clot or other material traveling from another site) event. "Secondly, FGF10 treatment in vivo decreased neuronal apoptosis and inhibited NF-κB signaling activation during ischemic stroke and thereby neuroinflammation (TNF-α and IL-6 production)." (PMID 26813160, 2016). "We think this issue may need further clarification with detailed works as it raises an important question about the complexity of FGF10-induced biological functions in ischemic stroke." (PMID 26813160, 2016). "We previously showed that FGF10 protects neuron against oxygen-glucose deprivation injury in vitro; however, the effect of FGF10 in ischemic stroke in vivo is unknown." (PMID 26813160, 2016). "Thus, we further investigated the potential role of FGF10 on ischemic stroke in vivo in this study." (PMID 26813160, 2016). "We also tested the effect of FGF10 in mice with mouse middle cerebral artery occlusion (MCAO), a widely-used in vivo ischemic stroke model." (PMID 26813160, 2016).
melanoma (1 paper, 2018). A malignant, usually aggressive tumor composed of atypical, neoplastic melanocytes. "In addition, five genes (FGF10, FGF2, MITF, PDGFC, and PDGFD) were involved in “Melanoma”, which might be associated with the two-end black pigmentation observed in BMX pigs, which differs from most Chinese domestic pigs with black coats (China National Commission of Animal Genetic Resources, 2011)." (PMID 29955027, 2018).
memory impairment (1 paper, 2023). "Neuronal apoptosis, a hallmark feature of AD associated with memory impairment, was investigated in vivo and in vitro to assess the effects of FGF10." (PMID 37503695, 2023).
osteosarcoma (1 paper, 2024). A usually aggressive malignant bone-forming mesenchymal neoplasm, predominantly affecting adolescents and young adults. "Somewhat surprisingly, OS-17 cells were insensitive to the growth factors PDGF-AA, PDGF-CC, FGF10, and NRG1, even at supraphysiological concentrations (100 ng/mL), which have been reported as having biological importance in osteosarcoma." (PMID 37676378, 2024).
ovarian tumors (1 paper, 2023). "Abnormal FGF10 expression is often closely related to tumor occurrence, and the expression of FGF10 in high-grade ovarian tumors is significantly different from that in normal tissues." (PMID 38274662, 2023).
pneumonia (1 paper, 2016). An acute, acute and chronic, or chronic inflammation focally or diffusely affecting the lung parenchyma, caused by an infection in one or both of the lungs (by bacteria, viruses, fungi, or mycoplasma.). "Intratracheal application of exogenous Fgf10, however, resulted in increased engagement of non-infected EpiSPC for tissue regeneration, demonstrated by improved proliferative potential, restoration of alveolar barrier function and increased survival following IV pneumonia." (PMID 27322618, 2016).
pulmonary edema (1 paper, 2023). Accumulation of fluid in the lung tissues causing disturbance of the gas exchange that may lead to respiratory failure. "Additionally, FGF10 exhibited its protective function in preservation of alveolar-capillary barrier integrity in high altitude pulmonary edema." (PMID 36969192, 2023).
renal fibrosis (1 paper, 2024). A final common manifestation of a wide variety of chronic kidney diseases characterized by glomerulosclerosis and tubulointerstitial fibrosis. "As the transcription of Fgf10 and Fgfr2 depends on AR signaling, exposure to DBP disrupted the Fgf10/Fgfr2 signaling pathway in the kidneys, this being a crucial factor in the development of renal fibrosis." (PMID 39728417, 2024).
small cell lung carcinoma (1 paper, 2020). Small cell lung cancer (SCLC) is a highly aggressive malignant neoplasm, accounting for 10-15% of lung cancer cases, characterized byrapid growth, and early metastasis. "A recent study on small cell lung cancer patients identified FGF10 amplification in 37.5% of patients and FGFR1 amplification in 25% of patients." (PMID 31958320, 2020).
Small patella syndrome (1 paper, 2022). "Small patella syndrome (SPS) is a rare autosomal dominant disorder caused by mutations in TBX4 gene which encodes a transcription factor of FGF10." (PMID 35216193, 2022).
spinal cord injury (1 paper, 2017). Penetrating and non-penetrating injuries to the spinal cord resulting from traumatic external forces (e.g., WOUNDS, GUNSHOT; WHIPLASH INJURIES; etc.). "However, little is known about the role of endogenous FGF10 in the recovery process after spinal cord injury (SCI)." (PMID 28981091, 2017).
squamous carcinoma (1 paper, 2025). "Notably, this mTOR-Wnt axis may have broader relevance: our prior work identified mTOR-mediated control of FGF10 in squamous carcinoma, suggesting a conserved paradigm where mTOR calibrates morphogen signaling across biological contexts." (PMID 40060475, 2025).
tendinopathy (1 paper, 2021). "Furthermore, gene variants of FOXP3, FCRL3, BMP4, and FGF3 and FGF10 as well as FGFR1 were analyzed in connection with tendinopathy in competitive athletes." (PMID 34366884, 2021).
teratoma (1 paper, 2010). A non-seminomatous germ cell tumor characterized by the presence of various tissues which correspond to the different germinal layers (endoderm, mesoderm, and ectoderm). "Our present two-week study falls short in answering some pending concerns, such as teratoma formation and immune response to FGF-10-stimulated ES cell-based therapy." (PMID 21203390, 2010).
thymoma (1 paper, 2021). A neoplasm arising from the epithelial cells of the thymus. "Several important genes associated with thymus development, such as CLDN4, FGF7 and FGF10, showed high expression in certain thymoma subtypes and TCs, suggesting their potential role in the development of TETs." (PMID 34568003, 2021).
thyroid (1 paper, 2022). "Furthermore, in FGF10 EX1mut/EX3mut transgenic mice with severe thyroid hypoplasia, allogeneic normal ECSs could induce orthotopic thyroid tissue regeneration when microinjected into the embryos of FGF10 EX1mut/EX3mut mice via blastocyst complementation." (PMID 36531472, 2022).
thyroid cancer (1 paper, 2018). "With this prospect in mind, it is reasonable to assume that Fgf10-mediated growth predominantly in the developing thyroid could be of relevance also to thyroid cancer development." (PMID 29361553, 2018).
trisomy 21 (1 paper, 2018). A chromosomal disorder consisting of the presence of an extra chromosome 21. "Like Trisomy 21 in humans, interruption of FGF10/FGFR2b signaling is the best demonstrated genetic link to DA in mice." (PMID 30473704, 2018).
venous ulcers (1 paper, 2020). "FGF-10 has been successful in improving the healing rate of non-healing venous ulcers." (PMID 32874798, 2020).
viral infection (1 paper, 2022). "In experiments using BO-ALI, we confirmed that basal cells survived after the viral infection, but also discovered that FGF10 is essential for their proliferation and differentiation." (PMID 35637255, 2022). "Therefore, FGF10 may be effective at regenerating bronchi damaged by viral infection." (PMID 35637255, 2022).
xerostomia (1 paper, 2018). Dryness of the mouth resulting from reduced salivary secretion. "FGF10 dose-dependence during development of salivary glands is further supported by the fact that mice heterozygous for Fgf10 have hypoplastic salivary glands and xerostomia (dry mouth)." (PMID 30505318, 2018).
tumor (44 papers, 2007 to 2026). "With regard to the size of tumors, FGF-10 gene upregulation was observed in 50 % of all tumors with size larger than 5 cm, and the tumor size was significantly associated with FGF-10 gene expression (P value < 0.05)." (PMID 31611737, 2019). "Moreover, we found a significant association between the expression of FGF-10 gene and tumor site (P value < 0.05)." (PMID 31611737, 2019). "In fact, the tumor size was significantly associated with FGF-10 gene expression (P value < 0.05)." (PMID 31611737, 2019). "However, emerging evidence suggests that FGF10 secreted from tumor-associated macrophages may play a role in promoting lung tumourigenesis." (PMID 30405704, 2018). "The upregulated genes, including WNT11, HAPLN1, FGF10, BBOX1, CXADR, NDP, and EREG are associated with tumor proliferation, migration, and cancer stemness." (PMID 35954313, 2022). "When comparing the gene profile of CAFs from two tumor foci for each one of these cases, we only found significant differences between CAFs populations for FGF10, IL17RB, and MMP2, evidencing a little variability within the multifocal PCa tumor focus." (PMID 35885510, 2022). "In detail, FGF1 and FGF10 were downregulated in most of the tumor types whereas FGF3, FGF5, FGF11, FGF19, FGF20, and FGF21 were upregulated in most of the tumor types." (PMID 32596330, 2020). "In this study, we aimed to investigate the FGF-10 gene expression in tumor tissues based on the pathological feature of tumor related to EMT and metastasis." (PMID 31611737, 2019). "Increased expression of FGF-10 has been described in several tumours, including those of the colorectum, prostate and breast." (PMID 19410332, 2009). "Postnatal overexpression of Fgf10 led to tumor formation and differentiation of epithelial tumor cells into a distal type II alveolar cell like phenotype." (PMID 18186922, 2008). "Second, we investigated whether there is any significant relationship between pathological characteristics of tumor and FGF-10 expression." (PMID 31611737, 2019). "Considering the tumor samples, we found an upregulation of FGF-10 gene expression in 52.1 % of all tumors in stage III and only in 9.09 % of all tumors in stage I. Also, there were an upregulation of FGF-10 gene expression in 50 % of all positive lymph invasion patients." (PMID 31611737, 2019). "VEGFC and fibroblast growth factor 10 (FGF10) may also participate in the process of tumor cell EMT." (PMID 31130595, 2019). "Moreover, the significant correlation between the FGF-10 gene expression with the size and site of the tumor indicates its importance in the prognosis and survival of CRC patients." (PMID 31611737, 2019). "FGF10 is a member of the fibroblast growth factor family of proteins, and is involved in a range of biological processes, including embryonic development and morphogenesis, cell growth and repair, tumor growth and invasion." (PMID 30175238, 2018). "In contrast to these data implicating FGF10 in skin carcinogenesis, previous work has suggested that FGF10-FGFR2b signaling may perform tumor-suppressive functions in the skin." (PMID 30405704, 2018). "Indeed, the ApcMin/+ intestinal and Fgf-10 lung models of adenoma formation may differ in their underlying mechanistic basis, but there are undoubtedly tissue-specific contributions affecting the emergent tumor phenotype(s) when Blm levels are genetically modulated in specific cellular compartments." (PMID 27413734, 2016). "Additionally, FGF10 overexpression can drive tumor formation as previously discussed, suggesting that the dosage of FGF10 is very important for proper prostate homeostasis." (PMID 24199173, 2013).
tumor (continued). "FGF2, FGF7 and FGF10, as members of the fibroblast growth factor family, are involved in various biological processes, including embryonic development, cell growth, tissue repair, tumor growth and invasion, and have been reported to be critical targets in the fibrosis process." (PMID 37275903, 2023). "In addition to these findings, our present result demonstrates that FGF-10 might correlate with tumor cell behavior; however, further studies are required to specifically determine its roles in cancer development and metastasis." (PMID 31611737, 2019). "In this study, we demonstrate that FGF7 and FGF10, likely through FGFR2IIIb, induce downstream β-catenin activation and its nuclear translocation in both post-liver bud embryonic hepatoblasts and Mat1a−/− tumor initiating stem cell line via AKT-dependent phosphorylation of Serine-552." (PMID 23308088, 2012). "CRC organoids were cultured in a customized growth factor‐reduced medium containing FGF10, A83‐01, SB202190, gastrin, and nicotinamide to better maintain original tumor features." (PMID 41503026, 2026). "Specifically, OncoPro medium was supplemented with 10 ng/ml HS FGF-10 for head and neck tumoroid cultures and with 10 ng/ml HS FGF-10 plus 10 nM gastrin I for pancreas tumoroid cultures; colorectal, lung, and breast tumoroids were cultured." (PMID 39890889, 2025). "The cell-type-specific (defined based on marker gene expression profiles and clustering analysis) expression of CD44, FGF2, FGF10, KDM6A, FN1, and MMP2 in the tumor microenvironment of UCEC was analyzed using the TISCH2 database." (PMID 39833941, 2025). "Although the role of FGFs in PDAC has been controversial, a set of good-prognostic LR pairs including FGF7, FGF10, and FGFR2 is proposed to exert a tumor suppressive function via reduced oxidative stress and activation of immune surveillance." (PMID 34522794, 2021). "Filtering of the digestion mix resulted in larger, partially digested tumor pieces that were further cultivated under serum-free conditions in advanced DMEM-F12 medium with supplements and beneficial cytokines (FGF-basic, FGF-10 and Nodal)." (PMID 30744205, 2019). "Some of these amplified genes are well-known tumor related genes, such as AKT2, FGFR3, FGF10, SDHA, CCNE1, PI3KCA, and etc." (PMID 28029662, 2017). "Our results demonstrate significant downregulation of FGF2 and FGF10 in UCEC, which may contribute to impaired wound healing and reduced tumor progression in these cells." (PMID 39833941, 2025). "Considering the site of tumors, FGF-10 gene expression showed increased levels in 69 % of all tumors located in the colon, and there was a significant correlation between FGF-10 gene expression and tumor site (P value < 0.05)." (PMID 31611737, 2019). "Positive feedback between Fgf10 and Fgfr2-IIIb has previously been reported during salivary gland development, and in nonmalignant tumors, Fgf7-mediated FGFR2-IIIb expression is thought to play a tumor-suppressive role by promoting epithelial differentiation." (PMID 30695023, 2019). "Immunohistochemical staining in the present study also revealed the expression of FGF7 and FGF10 mainly in the stromal cells rather than the tumor cells." (PMID 24002438, 2013). "One model that might explain this is that FGF22 might act to antagonise the tumour suppressive role of FGFR2b, by competing with the protective ligands FGF7 and FGF10." (PMID 22737238, 2012). "Since FGF10 is known to be secreted by fibroblasts and to bind specifically to the FGFR2-IIIb isoform expressed on epithelial cells, however, our findings would fit a model of paracrine tumor-stroma interaction." (PMID 21767389, 2011). "In contrast, Blm haploinsufficiency had no impact on tumor development, progression, or regression in a Ccsp/Fgf-10 transgenic model which overexpresses the growth factor Fgf-10 under control of the lung-specific Clara cell secretory protein (Ccsp) promoter (Boivin & Groden, personal communication)." (PMID 27413734, 2016).